MSTO2P (misato family member 2, pseudogene)
Synonyms: formerly MSTO2
Gene: Transcribed unprocessed pseudogene on chromosome 1 (155,745,829 to 155,750,137, forward strand). Ensembl gene ENSG00000203761.
Diseases named in the same sentence as MSTO2P in open-access papers:
MSTO2P is named in the same sentence as 8 diseases in open-access papers, as found by Europe PMC text mining. Sharing a sentence is not in itself a finding about the gene and the disease. The quoted sentences say what the papers report.
lung carcinoma (6 papers, 2017 to 2023). "With regard to this, a study on lncRNA misato homolog 2 pseudogene (MSTO2P) showed that it was considerably upregulated in lung cancer cells." (PMID 36899946, 2023). "LncRNA MSTO2P promotes lung cancer cell proliferation and autophagy by upregulating EZH2." (PMID 36105077, 2022). "The lncRNA MSTO2P promoted lung cancer cell proliferation and autophagy by upregulating EZH2." (PMID 32190662, 2020). "The knockdown of MSTO2P resulted in decreased levels of LC3-I, LC3-II, AGT5, and EZH2, leading to impaired processes of proliferation and autophagy in lung cancer cells." (PMID 36899946, 2023). "Similarly, the levels of EZH2 were increased in lung cancers as compared with normal tissues and its levels were correlated to the ones of the lncRNA MSTO2P, (a new positive regulator of EZH2 whose mechanism is unknown), data which were coherent since lncRNA MSTO2P can positively regulate EZH2." (PMID 31861179, 2019). "In network, 4 pseudogenes (RRP7B, RPLP0P2, MSTO2P and AFG3L1P) co-methylated with EZH2, suggesting an involvement in the progression of lung cancer." (PMID 28938616, 2017).
gastric cancer (2 papers, 2016 to 2022). A primary or metastatic malignant neoplasm involving the stomach. "It was reported pseudogene MSTO2P played an oncogenic role via targeting miR-335 level in gastric cancer." (PMID 35346226, 2022). "OR3A4, LOC84740, FCGR1C, and NCRNA00200 were upregulated in gastric cancer tissues, whereas MSTO2P, LOC344595, TUG1, and TYW3 were downregulated (P < 0.05)." (PMID 26863570, 2016). "OR3A4, LOC84740, FCGR1C, and NCRNA00200 were overexpressed in gastric cancer tissues, whereas MSTO2P, LOC344595, TUG1, and TYW3 were downregulated." (PMID 26863570, 2016).
osteosarcoma (2 papers, 2021 to 2023). A usually aggressive malignant bone-forming mesenchymal neoplasm, predominantly affecting adolescents and young adults. "Moreover, individuals with higher stages of osteosarcoma (stage III þ IV) showed elevated expression levels of MSTO2P." (PMID 34947885, 2021).
colorectal cancer (1 paper, 2024). A primary or metastatic malignant neoplasm that affects the colon or rectum. "A recent study explored the link between EZH2-mediated epigenetic silencing and ncRNAs, specifically the lncRNA MSTO2P in colorectal cancer." (PMID 38473229, 2024). "MSTO2P levels were high in colorectal cancer tissues and cells." (PMID 38473229, 2024).
COVID-19 (1 paper, 2023). A disease caused by infection with severe acute respiratory syndrome coronavirus 2. "Two genes were located at pleiotropic loci identified in cross-trait meta-analysis, including ABO (enriched in whole blood and shared by BC with all three COVID-19 phenotypes) and MSTO2P (enriched in muscle skeletal and pancreas)." (PMID 37636041, 2023).
hepatocellular carcinoma (1 paper, 2024). A malignant tumor that arises from hepatocytes. "It has been reported that the lncRNA pseudogene misato family member 2 (MSTO2P) affects cell proliferation, apoptosis, metastasis and invasion in hepatocellular carcinoma through the PI3K/AKT/mTOR pathway, thereby supporting the diagnostic and prognostic value of MSTO2P." (PMID 38473229, 2024).
tumor (2 papers, 2021 to 2022). "At last, rescue experiments proved the anti-tumor effect of inhibition of MSTO2P was partially recovered due to the knockdown of CDKN1A in HT-29 cells." (PMID 35346226, 2022). "Besides, knockdown of CDKN1A abolished the anti-tumor effect of inhibition of MSTO2P in HT-29 cells." (PMID 35346226, 2022).
cancer (1 paper, 2022). A tumor composed of atypical neoplastic, often pleomorphic cells that invade other tissues. "LncRNA misato family member 2 (MSTO2P) is considered a pseudogene and is upregulated in several cancers." (PMID 35346226, 2022). "Furthermore, lncRNA MSTO2P participates in the development of cancers." (PMID 35346226, 2022).